RDH12 (retinol dehydrogenase 12)
Description:
Retinoids dehydrogenase/reductase with a clear preference for NADP. Displays high activity towards 9-cis, 11-cis and all-trans-retinal. Shows very weak activity towards 13-cis-retinol. Also exhibits activity, albeit with lower affinity than for retinaldehydes, towards lipid peroxidation products (C9 aldehydes) such as 4-hydroxynonenal and trans-2-nonenal. May play an important function in photoreceptor cells to detoxify 4-hydroxynonenal and potentially other toxic aldehyde products resulting from lipid peroxidation. Has no dehydrogenase activity towards steroids.
Synonyms: SDR7C2; FLJ30273; LCA13; RP53
Tractability: PROTAC: ubiquitination databases record sites on it.
Gene: Protein-coding gene on chromosome 14 (67,701,886 to 67,734,451, forward strand). Ensembl gene ENSG00000139988.
Subcellular location: Endoplasmic reticulum membrane
Pathways (Reactome):
Disease: Defective visual phototransduction due to RDH12 loss of function
Sensory Perception: The canonical retinoid cycle in rods (twilight vision)
Gene Ontology:
Molecular function: 11-cis-retinol dehydrogenase (NADP+) activity; all-trans-retinol dehydrogenase (NAD+) activity; all-trans-retinol dehydrogenase (NADP+) activity; protein binding; alcohol dehydrogenase (NADP+) activity
Biological process: cellular detoxification of aldehyde; retinol metabolic process; visual perception; photoreceptor cell maintenance; retinoid metabolic process
Cellular component: endoplasmic reticulum membrane; photoreceptor inner segment; photoreceptor inner segment membrane
Genetic constraint (gnomAD): Loss-of-function variants: 17 observed, 29.59 expected, observed/expected ratio (o/e) 0.57, 90% interval 0.39 to 0.86. The upper end of that interval is the gene's LOEUF score, 0.86, which puts it in group 3 of 6, group 1 being the genes least tolerant of losing a copy. Missense variants: 372 observed, 390.91 expected, observed/expected ratio (o/e) 0.95, 90% interval 0.87 to 1.04. Synonymous variants: 194 observed, 170.7 expected, observed/expected ratio (o/e) 1.14, 90% interval 1.01 to 1.28.
Gene-disease validity (ClinGen):
ClinGen rates the evidence that RDH12 causes each of these diseases.
RDH12-related recessive retinopathy (autosomal recessive): Definitive. A retinopathy, typically severe, and early onset, caused by biallelic variants in the RDH12 gene.
Homologues: Orthologues: chimpanzee RDH12 (100% identical), macaque RDH12 (98% identical), dog RDH12 (93% identical), pig RDH12 (91% identical), rabbit RDH12 (90% identical), guinea pig RDH12 (89% identical), rat Rdh12 (87% identical), mouse Rdh12 (86% identical). Paralogues in human: RDH11 (71% identical), WWOX (40% identical), RDH16 (26% identical), HSD17B6 (25% identical), HSD17B11 (24% identical), HSD17B13 (24% identical), SDR9C7 (24% identical), DHRS9 (22% identical), HSD11B2 (22% identical), RDH5 (22% identical), SDR16C5 (22% identical), RDH10 (20% identical), and 13 more.
Diseases named in the same sentence as RDH12 in open-access papers:
RDH12 is named in the same sentence as 51 diseases in open-access papers, as found by Europe PMC text mining. Sharing a sentence is not in itself a finding about the gene and the disease. The quoted sentences say what the papers report.
Leber congenital amaurosis (22 papers, 2007 to 2026). Leber congenital amaurosis (LCA) is a retinal dystrophy defined by blindness and responses to electrophysiological stimulation (Ganzfeld electroretinogram (ERG)) below threshold, associated with severe visual impairment within the first year of life. "Bi-allelic pathogenic variants in the Retinol Dehydrogenase 12 gene (RDH12) cause extensive, early-onset, retina disease and comprise between 3% and 10% of cases of Leber congenital amaurosis (LCA), depending on the population studied." (PMID 39120885, 2024). "RDH12 mutations account for approximately 4% of autosomal recessive Leber congenital amaurosis (LCA)." (PMID 37569703, 2023). "Mutations of RDH12 can cause early onset severe cone-rod dystrophy, Leber congenital amaurosis, retinitis pigmentosa, and pseudocoloboma-like maculopathy." (PMID 38203675, 2023). "Just as the clinical presentations related to RDH12 mutations include Leber congenital amaurosis (LCA), early onset severe retinal dystrophy, autosomal recessive RP (ARRP), autosomal dominant RP, and cone-rod dystrophy." (PMID 34567070, 2021). "RDH12 mutations account for approximately 7% of disease in our cohort of patients diagnosed with Leber congenital amaurosis and early-onset retinal dystrophy." (PMID 22065924, 2011). "Mutations within RDH12 cause both recessive early onset Retinitis pigmentosa and Leber's congenital amaurosis." (PMID 17286855, 2007). "Variants in RDH12 have been previously linked to Leber congenital amaurosis (LCA) and ad-RP." (PMID 33634125, 2021). "LCA5 and RDH12 are associated with Leber congenital amaurosis (LCA), and MC is one of the phenotypes for LCA5-LCA and RDH12-LCA." (PMID 36429029, 2022). "Other diseases, most notablyPRPH2- and ROM1-associated patterndystrophy and RDH12-associated Leber congenital amaurosis(LCA), have been reported to exhibit a similar manifestation although not asconsistent as in ABCA4-associated retinopathy." (PMID 32278709, 2020). "Mutations in RDH12 are primarily associated with Leber congenital amaurosis (LCA), a severe early onset autosomal recessive retinal dystrophy, and accounts for 3.4–10.5% of all cases." (PMID 32322264, 2020). "The purpose of the workshop was to share perspectives on what is known about the RDH12-associated retinal dystrophies (RDs) and discuss the advancement of therapies, primarily gene therapy, for people with mutations in the RDH12 gene which cause Leber congenital amaurosis 13 (LCA13)." (PMID 32855876, 2020). "Mutations of RDH12 can cause an autosomal recessive childhood onset of retinal dystrophy termed as Leber Congenital Amaurosis (LCA)." (PMID 27879662, 2016). "It is worth to note that the mutation of the RDH12 gene is causal to early onset retinal dystrophy Leber congenital amaurosis (LCA), a severe inherited eye-disease with a still incompletely understood pathogenesis." (PMID 26437435, 2015). "Variants in RDH12 (MIM 608830) have been associated with autosomal recessive (AR) early onset severe retinal dystrophy/Leber Congenital Amaurosis (EOSRD/LCA), cone/cone-rod dystrophy, retinitis pigmentosa (RP), and macular dystrophy (MD); and autosomal dominant (AD) RP." (PMID 35491887, 2022). "Leber congenital amaurosis (LCA) is a severe early onset autosomal recessive retinal dystrophy, and mutations in the retinol dehydrogenase 12 (RDH12) gene (OMIM: 608830) account for approximately 10% of all cases." (PMID 34445569, 2021). "Variants in the retinol dehydrogenase 12 (RDH12) gene are commonly associated with Leber congenital amaurosis (LCA), a severe retinal dystrophy characterised by night blindness, nystagmus and central loss of vision in early childhood, eventually leading to complete blindness in adulthood." (PMID 34216980, 2021).
Leber congenital amaurosis (continued). "The list included genes associated with different forms of Leber congenital amaurosis, involved in disruptions in phototransduction (AIPL1), retinoid cycle (RDH12, RPE65), and transport across the photoreceptor connecting cilium (LCA5), as well as genes evidently interacting with AIPL1 (NUB1, AHR)." (PMID 38203368, 2023). "Although variations in RDH14 are benign and not disease causing, mutations in RDH5 and RDH12 are known to be associated with fundus albipunctatus and leber congenital amaurosis." (PMID 28450823, 2017). "Clinical features: RDH12-associated retinopathy has wide phenotypic variability; including early-onset severe retinal dystrophy/Leber Congenital Amaurosis (EOSRD/LCA; most frequent presentation), retinitis pigmentosa, cone-rod dystrophy, and macular dystrophy." (PMID 35491887, 2022).
Retinal dystrophy (13 papers, 2015 to 2025). Retinal dystrophy is an abnormality of the retina associated with a hereditary process. "–5 Although understanding of RDH12-associated retinal dystrophies is advancing, the exact mechanisms underlying the human disease are not fully understood, and the disease course and natural history are yet to be fully elucidated." (PMID 39120885, 2024). "USH2A was the most frequent gene associated with RP, RDH12 early-onset severe retinal dystrophy, ABCA4 Stargardt disease, PROM1 cone-rod dystrophy, and BEST1 macular dystrophy." (PMID 37217489, 2023). "Ar biallelic variants in RDH12 were first identified in three consanguineous Austrian families with severe retinal dystrophy." (PMID 33634125, 2021). "CERKL was the most common gene implicated in a Tunisian population with retinal dystrophy, while RDH12 was also common in the Israeli population with inherited retinopathies." (PMID 33921607, 2021). "Interestingly, 49 genes associated with retinal dystrophies were significantly differentially expressed in RDH12-AD (21%, n = 229), with 38 downregulated and 11 upregulated." (PMID 40365019, 2025). "Mutations in RDH12 are the underlying cause in 3–7% of retinal dystrophy cases." (PMID 34567070, 2021). "Thirty (60%) had RPGR-related retinal dystrophy, nine (18%) had ABCA4-Stargardt disease, five (10%) had KCNV2-related retinal dystrophy, three (6%) had RDH12-related retinal dystrophy, two (4%) had Achromatopsia, and one (2%) had Usher syndrome." (PMID 39641965, 2024).
cone-rod dystrophy (11 papers, 2015 to 2025). Inherited retinal dystrophies that belong to the group of pigmentary retinopathies. "The other IRD group included Stargardt's disease carrying ABCA4 variants, as well as individuals with Cone-Rod Dystrophy (CORD) or RP presenting with various genetic variants such as RDH12, RPGR, LCA5,CEP290, RP2, USH2A, and EYS." (PMID 38466290, 2024). "This novel heterozygous variant RDH12 c.763delG is associated with a rod-cone dystrophy with variable expression." (PMID 34031043, 2022). "Mutations in RDH12 gene have been found in patients with autosomal recessive retinitis RP, cone-rod dystrophy as well as macular dystrophy." (PMID 35162940, 2022). "New frameshift P variant c.[105delG];[105delG] in RDH12 was found in the index patient of F3 with cone-rod dystrophy (CRD)." (PMID 33634125, 2021). "Another study closely followed and reported 11 distinct RDH12 mutations in homozygosity or compound heterozygosity in 8/44 patients with LCA who were affected with the congenital severe yet progressive rod-cone dystrophy form of the disease." (PMID 26124963, 2015). "Moreover, cone-specific markers associated with predominantly cone diseases (achromatopsia, cone/cone-rod dystrophy, and macular dystrophy) were downregulated, suggesting cones are preferentially affected in RDH12-AD models." (PMID 40365019, 2025). "A new frameshift variant c.[105delG];[105delG] in RDH12 was found in F3 with cone-rod dystrophy." (PMID 33634125, 2021). "Clinical descriptors of the phenotype of patients with RDH12 mutations include LCA, early onset retinal dystrophy (EORD), autosomal recessive retinitis pigmentosa, cone rod dystrophy, and late onset cone rod dystrophy." (PMID 39120885, 2024). "Pathogenic variants in RDH12 have been shown to cause autosomal recessive LCA and EOSRD (LCA13, OMIM #612712), characterized by severe progressive rod-cone dystrophy with widespread RPE atrophy, bone-spicule pigmentation, vascular attenuation, macular atrophy and corresponding macular excavation." (PMID 35162940, 2022).
retinal degeneration (10 papers, 2011 to 2024). Degeneration of the retina. "In Drosophila melanogaster, absence of PDH results in progressive light-dependent loss of rhodopsin and retinal degeneration, and the expression of RDH12 in PCRs can suppress these defects." (PMID 36555080, 2022). "The RDH12 Families and Patients group has now expanded to include over 200 people from over 20 countries, united in their common goal to accelerate the path toward a treatment or even a cure for RDH12-associated retinal degenerations." (PMID 39120885, 2024). "These high confidence variants were found in ABCA4, CERKL, MAK, PEX6 and RDH12 genes associated with retinal degeneration, that could be sufficient to cause pathology." (PMID 39365799, 2024). "Mutations in RDH12 are associated with severe early onset retinal degeneration." (PMID 34445569, 2021). "Our bioinformatics analyses suggest that Env7p is a putative kinase with 29% identity with the human serine/threonine kinase STK16, and Env9p is a putative oxidoreductase with 40% identity with the human retinol dehydrogenase RDH12, a gene associated with retinal degeneration." (PMID 21912603, 2011). "Presentations focused on latest learnings and expectations for treatment of RDH12-associated retinal degenerations, and on how lessons from the licensed ocular gene therapy, voretigene neparvovec-rzyl (LUXTURNA) and from recent IRD clinical studies may be translated to RDH12." (PMID 39120885, 2024). "Similar to RDH12-related RP, the retinal degeneration in USH2A patients is later onset, developing from adolescence, compared to those with LCA." (PMID 34445569, 2021). "Pregabalin is a primary amine containing drug, commonly used to treat epilepsy, nerve pain, and anxiety, and was shown to protect Rdh12-/- knockout mice from light-induced retinal degeneration." (PMID 34445569, 2021). "It is thought that a lack of functional RDH12 results in a build-up of atRAL in the photoreceptors, causing toxicity and resulting in retinal degeneration." (PMID 34445569, 2021). "Two Rdh12 knockout mouse models were generated; however, both displayed a relatively mild phenotype, with normal retinal histology and no apparent signs of retinal degeneration." (PMID 34445569, 2021). "Combined deletion of retinal dehydrogenases, RDH12 and RDH8, results in mouse retinal degeneration." (PMID 33107823, 2020).
retinitis pigmentosa (8 papers, 2015 to 2025). Retinitis pigmentosa (RP) is an inherited retinal dystrophy leading to progressive loss of the photoreceptors and retinal pigment epithelium and resulting in blindness usually after several decades. "This powerful tool unravels disease mechanisms associated with a milder and late-onset retinitis pigmentosa, providing further insights into RDH12 function in the retina." (PMID 40365019, 2025). "Heterozygous variants in RDH12 cause a rare autosomal dominant (AD) retinitis pigmentosa." (PMID 40365019, 2025). "In addition, we report two cases with retinitis pigmentosa caused by RDH12 (c.524C > T) and PRPF4 (c.1273G > A) pathogenic mutations." (PMID 37264419, 2023). "These include variants in the NAD+ or NADPH dependent retinal dehydrogenases like RDH12 that cause LCA13 and the GTP synthesis enzyme IMPDH1 that causes retinitis pigmentosa." (PMID 33107823, 2020). "While few in vitro (cell lines overexpression WT or mutated RDH12) and in vivo (mutant mouse and zebrafish) models exist for autosomal recessive RDH12-retinopathies, no animal model has been created for autosomal dominant RDH12-related retinitis pigmentosa." (PMID 40365019, 2025).
achromatopsia (4 papers, 2024 to 2025). Achromatopsia (ACHM) is a rare autosomal recessive retinal disorder characterized by color blindness, nystagmus, photophobia, and severely reduced visual acuity due to the absence or impairment of cone function. "Stationary IRDs constituted 14.2% (3.1% albinism, 4.7% CSNB, 5.4% achromatopsia), variants causative for LCA were assigned to 8.5% (CEP290, GUCY2D, RDH12, CREB1, RPE65, RD3), 6% were annotated in RS1, and 3.1% were annotated in CHM." (PMID 39596324, 2024).
retinal disease (4 papers, 2023 to 2025). "The mutated RDH12 mRNA, which is insensitive to NMD, produces a 40-amino-acid shorter protein, with a 17-amino-acid sequence shared with the two other variants previously reported in autosomal dominant RDH12-retinal diseases." (PMID 40365019, 2025). "In the presence of biallelic recessive mutations in RDH12, human retinal disease presents with varying age of onset and phenotypic severity." (PMID 37569703, 2023). "Gene therapy approaches targeting other types of IRDs, especially RDH12 (retinol dehydrogenase 12)-associated retinal diseases, for which there is no available treatment, are being developed and already demonstrating promising results." (PMID 38276507, 2024).
retinoblastoma (4 papers, 2021 to 2024). A malignant tumor that originates in the nuclear layer of the retina. "We have successfully identified a few gene signature (CLUL1, CNGB1, ROM1 and RDH12) to predict the risk of invasion in retinoblastoma and therefore, in this study, we investigated the profiles of invasive risk panel between subtypes." (PMID 37777551, 2023). "It has been reported that CLUL1, CNGB1, ROM1, LRRC39, and RDH12 genes in different retinoblastoma subtypes are involved in the progression and development of the disease, which can be useful as biomarkers (M.)." (PMID 34646884, 2021). "Interestingly, the retinoblastoma invasion markers (CLUL1, CNGB1, ROM1 and RDH12) were predominantly higher in subtype 1b, suggesting subtype 1b retinoblastoma prone to be more invasive as compared with other subtypes." (PMID 37777551, 2023).
night blindness (3 papers, 2010 to 2021). Inability to see clearly in dim light. "Symptoms of night blindness were reported by 11 individuals, including CRB1 or TULP1 mutations (all individuals; three each group), RPGRIP1 or RPE65 mutations (two individuals each) and RDH12 mutations (one individual)." (PMID 29178642, 2017).
autosomal recessive retinitis pigmentosa (2 papers, 2010 to 2011). Autosomal recessive retinitis pigmentosa (RP) is an autosomally recessive inherited retinal dystrophy leading to progressive loss of the photoreceptors and retinal pigment epithelium and resulting in blindness usually after several decades. "Twelve additional patients with EORD or autosomal recessive retinitis pigmentosa with a phenotype consistent with RDH12 deficiency underwent RDH12 screening." (PMID 22065924, 2011). "Mutations in RDH12 have been associated with early-onset autosomal recessive retinitis pigmentosa." (PMID 21151602, 2010).
breast carcinoma (2 papers, 2021 to 2025). "Furthermore, we generated an expression risk score for each of the breast cancer patients in the METABRIC Discovery, Validation and TCGA sets using the seven genes RDH5, RDH8, RDH10, RDH11, RDH12, RDH13, RDH14." (PMID 33436820, 2021). "Based on the TCGA-TNBC dataset analysis, four out of the five model genes (SDS, RDH12, IDO1, and GLDC) demonstrated significantly elevated expression levels in breast cancer samples." (PMID 40217479, 2025). "To explore the expression patterns of the seven genes RDH5, RDH8, RDH10, RDH11, RDH12, RDH13, RDH14 in normal tissues as well as breast cancer tissue, we first drew a heat map of the expression levels of the genes across normal human tissues from GTEx portal." (PMID 33436820, 2021).
cervical cancer (2 papers, 2020 to 2023). A primary or metastatic malignant neoplasm involving the cervix. "For example, RDH12 has been shown to be differentially expressed in cervical cancer and RDH12 expression was negatively associated with tumor size and depth of cervical invasion." (PMID 37910143, 2023). "The expression of RDH12 was negatively associated with tumor size and infiltration depth in cervical cancer." (PMID 32920549, 2020).
diabetes (2 papers, 2019 to 2022). "In the present study, the overall effect of downregulation RDH12 and retinal dehydrogenase 1 in patients with diabetes appears to be associated with a poor prognosis of EC as more patients in the diabetic group had a high-grade stage 3 EC." (PMID 35454982, 2022).
early-onset retinal dystrophy (2 papers, 2011 to 2015). "To date, over 60 different RDH12 mutations have been reported predominantly in LCA patients but also in early-onset retinal dystrophy, in families with arRP, and in a family with autosomal dominant RP." (PMID 26124963, 2015).